MMP9 (matrix metallopeptidase 9)
Diseases named in the same sentence as MMP9 in open-access papers (continued):
Sharing a sentence is not in itself a finding about the gene and the disease.
ischemic stroke (continued). "Modulating MMP-9 or neutrophil infiltration processes could be a target for future investigations to improve the present thrombolytic therapy for ischemic stroke." (PMID 29724240, 2018). "MMP9 is upregulated in delayed and acute phases of post ischemic stroke models." (PMID 28086917, 2017). "Indeed, the correlation of MMP-9/TIMP-1 ratio with cerebral edema was even stronger than that of MMP-9 alone following ischemic stroke in rats." (PMID 26973468, 2016). "However, controversy still remains as to which cells are responsible for the bulk of the MMP-9 load following ischemic stroke." (PMID 26973468, 2016). "Inhibition of ASK1 could be an efficient strategy for attenuating MMP-9 activation and preventing neuronal cell death after ischemic stroke." (PMID 27642277, 2016). "Although, many studies have shown that ASK1 is linked to vascular injury and neuronal cell death after cerebral ischemia, it remains unclear whether ASK1 affects MMP-9 activation, which plays a crucial role in ischemic stroke." (PMID 27642277, 2016). "Findings from our current study indicate that EP1 blockade could represent a novel alternative strategy to protect the BBB from MMP-9 and MMP-3-associated breakdown following ischemic stroke." (PMID 26648273, 2015). "In conclusion, our findings suggest that MMP-9 -1562 genotypes are significantly associated with the risk of ischemic stroke in patients with and without T2DM." (PMID 26330106, 2015). "Antagonizing MMP-9 diminished cortical apoptosis, was associated with improved outcome after experimental SAH, and was recently postulated as potential therapy in ischemic stroke." (PMID 25887441, 2015). "In summary, chronic hyperglycemia aggravates hemorrhagic transformation after ischemic stroke through mitochondrial dysfunction and morphological alterations, partially via MMP-9 activation with ROS-independent manner; this leads to caspase-dependent apoptotic cell death in endothelial cells." (PMID 25133692, 2014). "This redistribution likely reflects multiphasic roles of MMP-9 in ischemic stroke." (PMID 23565108, 2013). "In addition, combination therapy with minocycline can suppress plasma levels of MMP-9 after ischemic stroke." (PMID 23565108, 2013). "MMP-9 mRNA expression in the blood following tPA treated ischemic stroke remains poorly studied." (PMID 20406488, 2010). "MMP-9 has been studied in ischemic stroke at both the protein and RNA level in blood and brain." (PMID 20406488, 2010). "Additionally, our data may provide a functional link between MMP-9, BDNF and their involvement in many brain pathologies, which has previously been implicated, for example, in addiction, schizophrenia, ischemic stroke, or even cochlear implantation." (PMID 40991708, 2025). "Another study also showed that an increase in serum MMP-9 levels during the acute phase of ischemic stroke contributed to an increased mortality and major disability rate, suggesting that serum MMP-9 could be a significant predictor of ischemic stroke prognosis." (PMID 37342100, 2023). "Thus, the ability of MSCs to improve the integrity of the BBB in ischemic stroke could be explained in part by a reduction in the infiltration of neutrophils into the lesion and, consequently, the reduced release of MMP-9 from these cells." (PMID 37511788, 2023). "MMP-9 is associated with BBB disruption in several diseases, including ischemic stroke, intracerebral hemorrhage and brain edema, and activation of MMPs could be provoked by oxidative stress and inflammatory cytokines, leading to tight junction disruption and reduced vasculature integrity." (PMID 35467388, 2022). "The MMP-9 gene is known to be associated with atherosclerotic plaque instability and the MMP-9 gene-1562C/T polymorphism (single-nucleotide polymorphism [SNP] rs3918242) leads to an increased risk of ischaemic stroke; however, there are some contradictory results as well." (PMID 35002488, 2021).
ischemic stroke (continued). "However, the usefulness of MMP-9 in predicting ischemic stroke should be studied further." (PMID 32982940, 2020). "Because matrix metalloproteinase-9 (MMP-9) is associated with the risk of many cardiovascular diseases, we investigated the relationship between single nucleotide polymorphisms (SNPs) in MMP-9 and the risk of Ischemic stroke (IS) in a southern Chinese Han population." (PMID 30992065, 2019). "However, it has also been reported that neither baseline MMP-9 levels nor the rate of MMP-9 increase had any association with the risk of HT in the setting of ischemic stroke." (PMID 26973468, 2016). "Additionally, mRNA samples in the present study were all from PBMCs, thus we suggest that ARG1 and MMP9 could be used as biomarkers for the detection of ischemic stroke." (PMID 27672514, 2016). "Similarly, in adult models of ischemic stroke, SB-3CT has been found to reduce infarct volumes and ameliorate behavioral and cognitive consequences, in part by antagonizing the injury-induced increase in MMP-9 and subsequent laminin degradation." (PMID 26588471, 2015). "Thus, our studies showing an MMP-9 reduction suggest that hNSC treatment could be a potential adjunct therapy following tPA treatment in the acute stage of ischemic stroke." (PMID 25418536, 2014). "For example, matrix metalloproteinases ('MMP') -9 (MMP-9) and -13 (MMP-13), derived in part from astrocytes may contribute to post-ischemic BBB dysregulation and MMP-9 inhibition partially protects against ischemic stroke, decreasing infarct size and BBB breakdown." (PMID 22112345, 2011). "Multiple studies indicate that the level of matrix metalloproteinase 9 (MMP-9) is significantly increased in the ischemic brain of mice, rats and ischemic stroke patients, which is mainly secreted by invasive neutrophils, and induced BBB damage." (PMID 40949877, 2025). "Our findings indicate that in experimental ischemic stroke with reperfusion, the duration of ischemia and r-tPA treatment significantly impacts the expression of MMP-2, MMP-3, and MMP-9, as well as the extent of ischemic brain injury and neurological outcomes." (PMID 39273389, 2024). "Our previous research has found that teriparatide can inhibit the formation of matrix metalloproteinase 9 (MMP9), reduce blood-brain barrier permeability, and improve the prognosis of ischemic stroke." (PMID 38770002, 2024). "No previous reports have clearly compared the time-dependent expression of different MMPs (MMP-9, MMP-3, MMP-2) after r-tPA treatment in ischemic stroke and their presence in neuronal or vascular compartments." (PMID 39273389, 2024). "For instance, PtNZs administered to mice following ischemic stroke were able to cross the damaged BBB, reduce matrix metalloproteinase-9 (MMP-9), and improve motor function." (PMID 39600701, 2024). "The expression levels of both MMP9 and ITGAM were quantitatively assessed in the ischemic stroke (IS) and control groups." (PMID 38637126, 2024). "Four and a half weeks after ischemic stroke, we measured the levels of MMP-2 and MMP-9 in plasma isolated from female and male offspring from mothers maintained on the CD, ChDD, or FADD prior to and during pregnancy and lactation." (PMID 39273042, 2024). "Preclinical studies have shown that SB-3CT, a more selective inhibitor targeting MMP-2 and MMP-9, can reduce infarct size and preserve BBB integrity in animal models of ischemic stroke." (PMID 38178909, 2023). "Data obtained during the simulation of ischemic stroke in animals via middle cerebral artery occlusion (MCAO) showed that in the first hours after ischemic injury, the content and activity of MMP-9 increased significantly in the focal zone." (PMID 37511788, 2023). "Animal experiments have shown that reducing neutrophil infiltration can reduce the release of MMP-9 in the brain and that inhibition of neutrophils can reduce BBB destruction and neurological deficits after ischemic stroke." (PMID 36447170, 2022).
ischemic stroke (continued). "Another panel of 5 markers, consisting of S100B, vWF, MMP9, B-type neurotrophic growth factor (BNGF), and monocyte chemoattractant protein 1 (MCP1), can distinguish patients with ischemic stroke from healthy controls with 92% sensitivity and 93% specificity." (PMID 36313479, 2022). "In models of subarachnoid hemorrhage (SAH), ischemic stroke, and traumatic brain injury, CsA has been shown to have a protective effect on the BBB by inhibiting CypA/MMP9 pathway and improving neurocognitive function, which was also noted in our model." (PMID 36337710, 2022). "Therefore, MMP-9 may be a potential prognostic biomarker for ischemic stroke." (PMID 36699006, 2022). "In clinical practice, dynamic changes of MMP-9 and BDNF were superior to baseline measurement in predicting the prognosis of ischemic stroke." (PMID 36092813, 2022). "Both MMP9 and PI3K/AKT signaling also contribute to the potential targets of luteolin action for the treatment of ischemic stroke-related inflammation." (PMID 33488758, 2021). "Of the MMP family, MMP9, has been confirmed to be the major MMP member altered after ischemic stroke." (PMID 34898370, 2021). "The patients suffer from the ischemic stroke exhibit the enhance level of MMP (MMP-2 and MMP-9) in the circulation." (PMID 34795593, 2021). "A related panel of S100B, MMP-9, vWF, and vascular cell adhesion molecule (VCAM) studied by the same group of researchers in 65 suspected ischemic stroke patients and 157 controls within 24 h of symptoms provided a sensitivity and specificity of 90%." (PMID 33633673, 2021). "Secreted MMP-9 degrades extracellular matrix proteins, increasing BBB permeability and hemorrhagic transformation in the brain after ischemic stroke." (PMID 32191628, 2020). "Compared with ischaemic stroke patients with both lower serum TIMP‐1 and MMP‐9 levels, the ORs were 2.83 (95% CI, 1.74‐4.60) for cognitive impairment defined by MMSE and 2.99 (95% CI, 1.81‐4.95) by MoCA in participants with both higher levels." (PMID 32431079, 2020). "The interactions between RAGE and MAPK during ischemic stroke promoted the expression of MMP-2 and MMP-9." (PMID 33584203, 2020). "MMP9 is a main endopeptidase mediating BBB disruption in various lesional and pathological processes, including ischemic stroke, and viral infection." (PMID 33411683, 2020). "MMP-9 and MMP-2 are responsible for BBB breakdown and hemorrhagic transformation after ischemic stroke." (PMID 32937836, 2020). "We further examined AQP4 and eNOS expression, MMP-9 enzyme activity, and possible signaling pathways for the role of NBP after ischemic stroke." (PMID 33510620, 2020). "Glycocalyx dysfunction, due to HPSE or MMP9, in several diseases and increased levels of HYAL1 and 2 in infarct lesions of ischemic stroke patients were reported." (PMID 33127645, 2020). "Patients with ischemic stroke exhibited drastic upregulation of ANRIL, hs-CRP, and MMP-9 in serum when compared to the control." (PMID 33192490, 2020). "Regulatory T cells ameliorate BBB damage after cerebral ischemia as well as hemorrhagic transformation after tPA administration following ischemic stroke in part by inhibiting CCL2 (monocyte chemoattractant protein 1) and MMP9." (PMID 30836997, 2019). "We demonstrated TGF-019 has sufficient sensitivity for the specific MMPs suspected in evoking HT during ischemic stroke, i.e., MMP2, MMP9, and MMP3." (PMID 30723388, 2019). "In conclusion, MMP9 was upregulated, and the PI3K/AKT signaling pathway was inactive during ischemic stroke." (PMID 30911000, 2019). "In contrast, MMP-9 is markedly elevated in the late phase of BBB disruption, which occurs at 24–72 h after ischemic stroke." (PMID 29724240, 2018). "MMP-9 and MMP-3 are key contributors to BBB disruption in the context of ischemic stroke since these proteases degrade the basal lamina and tight junction proteins essential to the barrier function of the neurovascular unit." (PMID 29527151, 2018).
ischemic stroke (continued). "It is interested that myeloperoxidase, a major component of neutrophil azurophilic granules, is MMP-9 postive, suggesting that neutrophils are the main source of MMP-9 following ischemic stroke." (PMID 29724240, 2018). "Following an ischemic stroke, breakdown of the BBB, vasogenic edema, and hemorrhagic conversion are mainly mediated by MMPs, in particular MMP-3 and MMP-9, which have been shown to be critical in inflammation-mediated neurovascular damage." (PMID 29527151, 2018). "Although different types of MMPs act differently, there is accumulating evidence that MMP-2, MMP-9, and MMP-12 are involved in the pathogenesis of BBB disruption and cerebral edema formation during ischemic stroke." (PMID 30131754, 2018). "MMP-9 contributes to BBB dysfunction by degrading TJ proteins under pathological conditions such as ischemic stroke and we have reported that brain pericytes, in particular among the cell types that constitute the BBB, release MMP-9 after thrombin stimulation." (PMID 28489922, 2017). "Our report shows that SLI treatment prevent brain injury after ischemic stroke by decreasing the expression of RAGE, MMP9 and inflammatory factors (COX-2, TNF-α and ICAM-1) in T1DM + MCAO rats." (PMID 28486941, 2017). "The TJs are reportedly degraded in I/R mainly by MMP-9 which is the predominant protease involving in BBB disruption following ischemic stroke." (PMID 28690765, 2017). "The use of MMP inhibitors to improve outcome in ischemic stroke and acute myocardial infarction AMI has been investigated, while neutrophil-derived MMP-9 was also indicated to trigger aortic dissection." (PMID 27610138, 2016). "Previously there were found higher circulating levels of MMP-9 and MMP-10 and TIMP-1 in ischemic stroke patients than in controls." (PMID 26162891, 2015). "We determined the effect of hNSCs on MMP-9 and MMP-2, proteins that participate in BBB breakdown following ischemic stroke." (PMID 25418536, 2014). "Matrix metalloproteinase 9 (MMP9), a zinc metalloproteinase enzyme involved in extracellular matrix degradation and primarily expressed by neutrophils, was significantly upregulated following ischemic stroke." (PMID 39915908, 2025). "In ischemic stroke, HSP70 exerts neuroprotection by inhibiting mitochondrial apoptosis via Bcl-2 upregulation and caspase-3 suppression while concurrently stabilizing the blood–brain barrier (BBB) through matrix metalloproteinase-9 (MMP-9) inhibition." (PMID 41415579, 2025). "Based on network pharmacological analysis, the core targets of AS-TMP combination for anti-ischemic stroke are TIMP-1, VEGFA, MMP9, etc., which are mainly related to apoptosis, cell proliferation, and vascular smooth muscle cell proliferation, focusing on the VEGF signaling pathway." (PMID 40869300, 2025). "During ischemic stroke, microglia produce pro-inflammatory cytokines such as tumor necrosis factor (TNF), interleukin 1 beta (IL1β), interleukin 6 (IL6), and proteolytic enzymes such as matrix metalloproteinase 9 (MMP9)." (PMID 40676515, 2025). "may exert therapeutic effects in ischemic stroke by downregulating AQP4, which in turn inhibits the upregulation of MMP-9 and suppresses the water flux across brain microvascular endothelium to astrocytes." (PMID 41409597, 2025). "Mechanistically, we identified that IFNβ attenuated delayed tPA-induced brain injury exacerbation, BBB disruption aggravation, and HT induction in ischemic stroke, and these protective effects were partly mediated through IFNβ-exerted suppression of MMP3 and MMP9 in the ischemic brain." (PMID 37063896, 2023). "Previous preclinical and clinical studies have shown promising results, suggesting that MMP-9 and MMP-2 may predict ischemic stroke outcomes, including hemorrhagic transformation (HT) and cerebral infarction volume." (PMID 37675160, 2023).
ischemic stroke (continued). "Neutrophils, microvessels and brain resident cells are major sources of MMP-9 activation contributing to hemorrhagic transformation in the presence or absence of t-PA during ischemic stroke." (PMID 35477576, 2022). "Some studies have reported that MMP9 may be one of the most promising biomarkers for assessing the BBB permeability and predicting hemorrhage transformation in ischemic stroke." (PMID 36061592, 2022). "In rtPA-administered ischemic stroke patients, Gołąb and his coworkers revealed that plasmin, which is known to be activated by rtPA, increases MMP-3 activity and influences the subsequent activation of MMP-9." (PMID 35163322, 2022). "Therefore, lower MMP-9 levels can reduce BBB breakdown, reduce secondary tissue damage, and improve neurological prognosis and survival after ischemic stroke." (PMID 34335600, 2021). "In conclusion, the present findings suggest that high plasma levels of MMP-9 are associated with VBE and independent of VAD, and that MMP-9 predicts the occurrence of ischemic stroke in patients at higher risk of posterior circulation ischemic events." (PMID 32982940, 2020). "Targeting the COX-2/MMP-9 pathway could represent a promising strategy to reduce neuroinflammatory events in order to preserve the BBB integrity and ameliorate ischemic stroke injury." (PMID 32973660, 2020). "Interestingly, our recent study has demonstrated that the brain infarct volume was remarkably reduced in MMP9 knock out (i.e., MMP9−/−) mice as compared with that of wild type (i.e., C57BL/6, simply written as B6) mice in the setting of ischemic stroke (IS)." (PMID 32867392, 2020). "For example, we have highlighted above the likely role of MMP-9 in acute post-ischemic NVU compromise, however, evidence also suggests that MMP-9 makes a critical contribution to the delayed phase reparative response to ischemic stroke." (PMID 32038147, 2019). "Additionally, activated matrix metalloproteinases (MMPs), such as MMP-2, MMP-3, MMP-7, and MMP-9, induce BBB disruption in experimental ischemic stroke and severe inflammatory response following septic shock." (PMID 31547411, 2019). "The expression of MMP9 mRNA showed a tendency to be increased in the post-ischemic stroke EcoHIV-infected brain; nevertheless, these changes were not statistically significant." (PMID 31043599, 2019). "Previous studies found that neutrophil was the major source of MMP-9 acting on the BBB, which may result in symptomatic HT and poor outcome after ischemic stroke." (PMID 31920933, 2019). "Ischemic stroke induces NOX4 activated, and previous research revealed that inhibition of NOX4 could suppress the enhanced level of MMP-9 induced by tMCAO." (PMID 28690765, 2017). "MMP-9 and MMP-3 are two MMPs involved in acute injury in ischemic stroke." (PMID 26648273, 2015). "In addition, the expression of iNOS can induce the expression of matrix metalloproteinase 9 gene (matrix metalloproteinase, MMP-9), MMP-9 can decompose collagen components in atherosclerotic plaque, leading to instability of atherosclerotic plaque and eventually leading to ischemic stroke." (PMID 39974357, 2025). "In vivo experiments and the levels of MMP-9 and TIMP-1 in serum and the infarcted cortex were determined through multiple strategies, including ELISA, immunohistochemistry, RT-PCR, and Western blotting, which were the key factors closely related to BBB injury in ischemic stroke." (PMID 40869300, 2025). "Moreover, MMP-9 may play a deleterious role in acute brain injury during the early stage of ICH and ischemic stroke; therefore, the inhibition of MMP activity during the critical period may improve brain injuries." (PMID 34067678, 2021). "However, it is not clear which downstream effectors of COX-2 mediate MMP-9 expression/activation in ischemic stroke." (PMID 32973660, 2020).